RN7SKP286 (RN7SK pseudogene 286)
Gene: Miscellaneous RNA gene on chromosome 2 (138,863,597 to 138,863,895, reverse strand). Ensembl gene ENSG00000222826.
Homologues: Orthologues: chimpanzee 7SK (97% identical). Paralogues in human: RN7SKP243 (76% identical), RN7SKP189 (75% identical), 7SK (74% identical), RN7SKP47 (74% identical), RN7SKP78 (74% identical), RN7SKP180 (74% identical), RN7SKP237 (74% identical), RN7SKP48 (74% identical), RN7SKP71 (74% identical), RN7SKP203 (74% identical), RN7SKP269 (73% identical), RN7SKP50 (73% identical), and 284 more.